TNF (tumor necrosis factor)
Diseases named in the same sentence as TNF in open-access papers (continued):
Sharing a sentence is not in itself a finding about the gene and the disease.
cancer (continued). "Based on our research, IL-35 could represent a novel treatment modality for many inflammatory diseases or cancer, based on its anti-TNF-α effects." (PMID 30061878, 2018). "Moreover, TNF-α is responsible mainly for the metabolic changes in lipid metabolism typical of advanced cancer patients, particularly those with cachexia." (PMID 30294279, 2018). "Shortly after cancer treatment, higher levels of sTNF-RII were associated with increased memory complaints, and on average 5 years after cancer treatment, elevated IL-6 and TNFα levels were associated with worse verbal memory." (PMID 30442190, 2018). "Modulation of autocrine TNF-α can sensitize cancer cells to cisplatin." (PMID 30140374, 2018). "On one hand, TNF-α could promote cancer due to its activation of cancer-promoting pathways such as NF-κB and its correlation with increased angiogenesis, cell growth and metastasis." (PMID 29996539, 2018). "TNF-α provides a good example of how interactions between cancer and stroma aid in OC metastasis." (PMID 30061485, 2018). "MyoD mRNA was reduced by TNF-α, but the MyoD mRNA level was increased in cancer cachexia muscle." (PMID 30300394, 2018). "Moreover, recombinant human TNFα (rhTNFα) has been tested as a systemic treatment of cancer patients in several phase I and phase II clinical trials." (PMID 29506556, 2018). "Because a TNF-β-induced inflammatory microenvironment promotes migration of CRC cells, we investigated whether TNF-β increased formation of cancer stem cells (CSCs) and whether resveratrol could modulate TNF-induced CSC formation." (PMID 30002278, 2018). "Lipases may be used as digestive aids and as the activators of Tumor Necrosis Factor (TNF) to treat malignant tumors." (PMID 29666707, 2018). "Cancer cells, regarded as exogenous factors, could induce the production of inflammatory cytokines, such as interleukin‐6 (IL‐6), tumor necrosis factor (TNF) and vascular endothelial growth factor (VEGF)." (PMID 30259688, 2018). "Gene set enrichment analysis and iPathway analysis identified signaling pathways with major implications to the pathobiology of cancer (e.g. TNFα, IFN, IL6/STAT, NF-κB) that are enriched in cisplatin-resistant ALDHhighCD44high cells, when compared to control cells." (PMID 29861860, 2018). "Likewise, a recent study suggested that another pro-inflammatory cytokine, TNFα, which is secreted by macrophages, induces stabilization of PD-L1 on cancer cells through COP9 signalosome subunit 5 (CSN5)-mediated de-ubiquitination." (PMID 30062558, 2018). "Thus, our overall results substantiate the possibility that MDM2 can promote the expression of MMP9 through activation of TNF-α pathway to support the invasive behavior of the cancer cells." (PMID 29748481, 2018). "Importantly, such resistance to inflammation-associated colon tumorigenesis in Mx1-Cre;Gankyrinf/f mice was associated with a significant reduction of pro-inflammatory responses (IL-17 and TNF-α) and expression of cancer stem cell markers (Bmi1 and Sox9)." (PMID 28160571, 2017). "Our results strongly suggest that the integrated pathway of TGFβ/Snail with TNFα/NFκB may be the principal axis that links cancer cells to their microenvironment during the EMT process and results in poor prognosis in CRC patients." (PMID 28687755, 2017). "In fact, being a double sword tool, TNF-α may play a defensive role by stimulating NK and cytotoxic T lymphocytes, but can also be “offensive” acting as mediator of cancer development through chronic inflammation promotion." (PMID 28222785, 2017).
cancer (continued). "Previous reports showed that the TNF-α could elevate ITGA5 expression via the NF-κB pathway in cancer." (PMID 28629363, 2017). "Previous study revealed that TNF-α could increase the sensitivity of cancer cells to cisplatin-induced cell death by NF-κB signaling pathway." (PMID 28129775, 2017). "GSC also might ameliorate adverse side effects and drug resistance that occurred in TNFα cancer therapy." (PMID 29379440, 2017). "While its early detection and prevention is important, salivary cytokines expression, specifically of Interleukin-8 (IL-8), Interleukin-6 (IL-6) and Tumor necrosis factor (TNF-α), does contribute to the pathogenesis of cancer and these cytokines serve as potential biomarkers." (PMID 28397778, 2017). "Traditionally a cancer drug, Etanercept may lower the effects of heightened levels of tumor necrosis factor alpha and deleterious inflammation." (PMID 29311768, 2017). "TNF-α shown to be an important cytokine mediator of cancer metastasis in murine models." (PMID 29219852, 2017). "TNF-α was discovered in 1975 as a serum factor inducing haemorrhagic necrosis in tumors and, therefore, this cytokine was proposed as a potential anti-cancer agent." (PMID 29276511, 2017). "Moreover, studies using TNF-α blocking antibody demonstrated that pro-inflammatory cytokine TNF-α was indispensable in supporting CM2-induced EMT to drive cancer cells migration and invasion." (PMID 28170411, 2017). "Therefore, TNF-α has been used as an antitumor agent previously because of its broad spectrums of cytotoxic effects against a variety of cancer cells, including colorectal cancer, melanoma and sarcoma." (PMID 28127258, 2017). "A remarkable difference was revealed between MCF-7 cells exposed to CM derived from TNFα + TGFβ1-stimulated MSCs (Group 4) and cancer cells exposed to the two other relevant treatments: CM of vehicle-treated MSCs (Group 3) or to the two cytokines only (Group 2)." (PMID 28553282, 2017). "We showed IFN-γ and TNFα can induce cancer cell death after 96 hours’ incubation." (PMID 29212184, 2017). "Current clinical practice could be improved if encouragement to engage with all cancer screening programmes was included in anti-TNF guidelines, particularly as most participants were unaware that anti-TNF would be stopped should they develop cancer." (PMID 28526972, 2017). "A commonly studied pro-inflammatory cancer biomarker is TNF-α." (PMID 28620703, 2017). "It remains inactive by the inhibitor of κB (IκB) in the cytosol and could be activated by various carcinogenic factors including tumor necrosis factor-α (TNF-α) in cancer cells." (PMID 28409156, 2017). "The inflammatory cytokines released by immune cells in response to the presence of the cancer, such as interleukin-1β(IL-1β), interleukin-6 (IL-6) and tumor necrosis factor-α (TNF-α), have been shown to play a key role in the disturbances of appetite and body weight control." (PMID 29207625, 2017). "All of these reports support our finding that the integrated pathway of TGFβ/Snail with TNFα/NFκB might be the key to the interactions between cancer cells and their microenvironment and their effects on the EMT and CRC prognosis." (PMID 28687755, 2017). "TNF-α has been known to induce DR6 in several cancer cell lines." (PMID 28348459, 2017). "Alterations in TNF-α gene expression or TNF-α cytokine release lead to a variety of cancers." (PMID 28881857, 2017). "The mechanisms of TNFα-induced EMT in cancer cells have been well studied." (PMID 29109804, 2017).
cancer (continued). "Furthermore, our results implicate an important role for TNF-α-producing cytotoxic T-cells in mediating the anti-cancer effects of immune checkpoint inhibitors when combined with SMCs." (PMID 28198370, 2017). "Thus, from these initial experiments we decided to go on to compare the maturation cocktail containing the GMP-grade poly I:C Hiltonol© in combination with IFNγ and R848, with TNFα alone that has been used by us and others in earlier cancer DC vaccine trials." (PMID 28601925, 2017). "TNF and IL6 have been well defined as inflammatory cytokines in cancer-associated inflammation." (PMID 28467300, 2017). "A systematic review of epidemiologic studies that included 22 articles also did not demonstrate an association between TNF inhibitor use and solid tumors in a population without a previous cancer diagnosis." (PMID 28717771, 2017). "Taking together, these results concluded that some inflammatory cytokine, such as TNF-α, might promote cancer-endothelial fusion through up-regulation of fusogenic protein syncytin-1 expression." (PMID 28112190, 2017). "Furthermore, production of TNF-α and IL-12 cytokines plays important roles in macrophage-mediated immune responses to pathogens and cancer, and the observation that TLR agonists and IFN-γ synergize for this function fits well with previous studies." (PMID 29123526, 2017). "Subsequently, TNFα was investigated as a therapeutic agent for cancer treatment." (PMID 28662099, 2017). "Moreover, two modules, including regulation tumor necrosis factor production and Ras protein signal transduction module, which have important roles in cancer, were unique to the primary tumor and portal vein tumor thrombus respectively." (PMID 29387082, 2017). "Also, patients with cancer are excluded from clinical trials with TNF inhibitors because of a concern over a potentially increased risk of developing cancer." (PMID 28717771, 2017). "Our findings demonstrating the joint power of TNFα + TGFβ1 + the factors they induce in MSCs on cancer cells provide proof-of-concept to the fact that MSCs are strongly affected by their microenvironment, and as a result secrete soluble mediators that modify their surroundings." (PMID 28553282, 2017). "In England, the decision to reimburse a medicinal product is made by different commissioners depending upon their therapeutic class, e.g., biosimilars of cancer drugs will be reimbursed by National Health Service England and biosimilars of TNF-alpha inhibitors by clinical commissioning groups." (PMID 29284064, 2017). "In addition, the quantitative loss of TRAF2-associated cIAP1 following bivalent IAP antagonist treatment correlated with inhibition of TNF-stimulated p65/NF-κB nuclear translocation and gene transcription in the cancer cell lines tested." (PMID 28149532, 2017). "In a cancer setting, tumors are often characterised by elevated levels of cytokines produced and secreted by the classical pathway, including two proinflammatory cytokines, TNF and IL-1β, which commonly trigger its activation." (PMID 28607534, 2017). "Numerous studies have suggested that polymorphisms in genes encoding inflammatory response factors, such as TNF-alpha -308G>A, IL6 -174G>C, and NFKBIA -826C>T may contribute to cancer susceptibility." (PMID 28039461, 2017). "The activation of such transcription factors initiates the expression of various target genes contributing to cancer progression by enhancing proliferation (IL-1, TNF-α, GM-CSF, Cyclin D1), evading apoptosis (BCL2, TRAF2, BCL3) and promoting cell invasion (IL-1, IL-6, TNF, MMPs)." (PMID 28427184, 2017). "Analogously, adipose tissue also influences cancer progression, particularly for its capacity to act as an endocrine system releasing and controlling biologically active substances (e.g. leptin, adiponectin, TNF-α, etc.)some of which are upregulated in cancer." (PMID 28752333, 2017). "Previous studies showed that TNF-α and IL-1β are essential for bacterial cancer therapy." (PMID 27835896, 2016).
cancer (continued). "Since we observed that CAFs can be activated to express TRAIL and ISs by inflammatory stimulation such as DNA fragment (poly(dA:dT)) or TNF-α, cancer cell death may create the feed-forward stimulation we observe here." (PMID 27077807, 2016). "TNF has been reported involved in the cancers development and progression in preclinical models." (PMID 27349736, 2016). "TNF is an important infectious agent in inflammation progression as well as cancer development." (PMID 28115787, 2016). "Although the mechanisms underlying malignant cells in manipulating the macro environment and the metabolic pathway in cancer hosts, several inflammatory cytokines, including interleukin-6 and tumor necrosis factor-α, have been shown, in preclinical tumor models, to induce cancer cachexia." (PMID 26879126, 2016). "Third, in some cancer types, since the number of relevant original documents was limited, there was not enough power to identify the relationship between TNF-α T-857C variant and cancer risk." (PMID 28115787, 2016). "To conduct this study we used cancer cell lines that produced high levels of TNF network proteins." (PMID 26871292, 2016). "Our study revealed that IL-4 antagonized the stimulatory effect of TNF-α on DC’s migratory and immuno-stimulatory functions in vitro, an effect that might impair the potential efficacy of DCs used as vaccines for cancer immunotherapy in vivo." (PMID 27080531, 2016). "Besides, in AOM/DSS-induced CAC mice model, the protein level of TNF-α is markedly elevated, which indicates the connection between inflammation and cancer." (PMID 26910375, 2016). "TNF-α was named for its ability to induce necrosis in some experimental cancers." (PMID 27835602, 2016). "The combined antiangiogenic and anti-TNF-α properties of thalidomide may represent apromising strategy for cancer treatment." (PMID 27303908, 2016). "Thus, by concomitant stimulation of both death receptor systems IFNα/Smac mimetic combination treatment is an effective strategy to induce cell death in TNFα- or TRAIL-responsive cancers." (PMID 26788912, 2016). "This suggests that the downregulation of iNOS, TNFα and IFNγ in MAMs in our model may occur through a direct interaction between LTβ on cancer cells and the LTβR on MAMs." (PMID 27203741, 2016). "As the addition of rutin and hyperoside reduced both TNFα and IL6, and previous work has shown that levels of TNFα are related to levels of OPG in cancer, OPG may have decreased as a result of lower levels of TNFα and IL6." (PMID 27136576, 2016). "The influence of IL-10 on more severe cancer disease is explained by antagonistic effect of IL-10 on the formation of pro-inflammatory cytokines (IL-6, TNF, IL-1α, IL-1β, IL-12) and inhibition of the inflammatory response, which plays an important role in the development of cancer." (PMID 27547238, 2016). "A further involvement of the TNF-α signaling in the ­anticancer effect of resveratrol is associated with the radio- and chemoinducible cancer gene therapy vector “Ad.Egr-TNF,” a replication-deficient adenovirus expressing human TNF-α under control of the early growth response (Egr)-1 promoter." (PMID 27148534, 2016). "Low concentration of TNF can promote the development of inflammation-related cancers." (PMID 27057094, 2016). "Previous reports have identified that TNF-α stimulates EMT in many cancer cells." (PMID 26683365, 2016). "Angiopoietin-1 (Ang1), a strong activator of intracellular PI 3′-kinase/Akt, was also demonstrated that it may be useful as an inhibitor of TNF-α-induced inflammation and cancer progression." (PMID 27713121, 2016). "TNFα exerts different actions in cancer therapy depending on the dosage used." (PMID 27342639, 2016). "Several lines of evidence have shown that TNF can be considered as an anti-cancer agent." (PMID 27791983, 2016). "TNFα has been previously reported to correlate with the extent of disease in cancer patients." (PMID 27713151, 2016).
cancer (continued). "Notably, the overexpression of LTβ in cancer cells significantly reduced the expression of iNOS, TNFα and IFNγ in parenchymal MAMs by 35%, 79% and 25%, respectively, implicating LTβ in polarization of MAMs towards the M2 state." (PMID 27203741, 2016). "In the ubiquitin-proteasome proteolytic pathway, two muscle-specific E3 ligases, MAFbx and MuRF-1, play pivotal roles in the degradation of myofibrillar and intracellular proteins, and their expression during cancer cachexia is regulated by pro-inflammatory cytokines such as TNF-α and IL-6." (PMID 27064118, 2016). "According to previous studies, TNFα induced NF-κB signaling could counteract TNFα-induced apoptosis while IFNγ could inhibit NF-κB activation and the expression of downstream apoptosis inhibitors, finally sensitizing the cancer cells to TNFα treatment." (PMID 27342639, 2016). "TAM also produce some factors, such as interleukin-6 (IL-6), tumour necrosis factor-α (TNF-α), which may activate some important signaling pathways in cancer cells and stimulate cancer metastasis." (PMID 27793010, 2016). "Our study also highlights the question of whether other inflammatory cytokines, for instance, TNF or IL-6 (both also induced by ingenol mebutate), are also involved in the anti-cancer efficacy of ingenol mebutate." (PMID 27100888, 2016). "On the one hand, TNF is an inflammatory mediator and the inflammatory process itself can lead to cancerous diseases; hence, inhibiting TNF, like other proinflammatory molecules, can be beneficial in the aspect of cancer initiation and progression." (PMID 28083070, 2016). "TNF-α in cancers is a master regulator of inflammation and the cytokine network." (PMID 27835602, 2016). "Notably, M2-macrophages produce multiple growth factors (such as EGF, FGF, HGF, PDGF, and TGFβ) and pro-inflammatory cytokines (including interleukin-1, interleukin-6, interferons, and TNFα) to stimulate the growth, migration, and invasiveness of cancer cells." (PMID 27276704, 2016). "Furthermore, we have demonstrated how autocrine CXCL12/CXCR4 signaling sustains this cytokine network through induction of TNF and that key pathways in cancer-related inflammation and NOTCH signaling appear to be part of this autocrine malignant cell network." (PMID 26871292, 2016). "Proinflammatory factors, such as TNF-α, have been shown as key mediators of cancer cachexia." (PMID 27378829, 2016). "Further research is needed to fully elucidate the role of specific mediators such as TNF-α in this process and to evaluate whether reducing the postoperative inflammatory response will reduce migration potential of cancer cells." (PMID 26819599, 2016). "Collective evidence has shown that TNF-α is a key mediator of inflammation and cancer." (PMID 26881177, 2016). "The ability of DpC to increase TNFα in tumors could also promote the endogenous immune response to mediate enhanced cancer cell apoptosis." (PMID 27678372, 2016). "The insensitive parameters, which can hardly increase the critical dose of TNF-α to induce apoptosis, can hardly cause cancer and therefore should frequently correspond to genes without mutations." (PMID 27129147, 2016). "Measurement of IL‐1β, IL‐6, and TNFα serum levels may help identify early cancer progression among patients with CRP <5 mg/L in routine practice." (PMID 26799163, 2016). "The association between sTNFR1 and sTNFR2 and mortality may have several explanations, as TNF-α and its soluble receptors are important in several elementary pathological processes not only in cardiovascular disease but also cancer." (PMID 26928194, 2016). "Notably, the choice of biomarkers within this study included several that play important roles in cancer, including TNFα and the stem cell differentiator GM-CSF." (PMID 27170831, 2016).